WT1 (WT1 transcription factor)
Diseases named in the same sentence as WT1 in open-access papers (continued):
Sharing a sentence is not in itself a finding about the gene and the disease.
ovarian carcinoma (continued). "Initial in vitro experiments were undertaken to ascertain staining of SKOV3 and MDAH274 ovarian cancer cell lines with AE1/AE3 (CK+ antibodies), used widely in NHS histopathology laboratories for diagnosis; as well as WT-1, which is an ovarian-specific stain." (PMID 31319587, 2019). "The subgroup analyses revealed that the expression of WT1 predicted the poor DSS (metaHR = 1.82, 95% CI = 1.42–2.73), and DFS/RFS/PFS (metaHR = 2.51, 95% CI = 1.81–3.48) in patients with ovarian cancer." (PMID 29995811, 2018). "First, SHMT1 is necessary for ovarian cancer tumor growth and progression, and SHMT1 expression is regulated by transcription factor WT1." (PMID 28288142, 2017). "SHMT1 promoter analysis identified transcription factor Wilms tumor 1 (WT1) binding sites, and WT1 knockdown resulted in reduced SHMT1 transcription in ovarian cancer cells." (PMID 28288142, 2017). "The ovarian epithelial inclusion cysts in Hoxa5−/− mice also express the ovarian cancer markers PAX8 and WT1 suggesting that they constitute preneoplastic lesions and that the loss of Hoxa5 function confers ovarian cancer predisposition." (PMID 29615582, 2016). "Subgroup analyses by cancer type showed that WT1 positive expression had an unfavorable impact on DFS/RFS/PFS for patients with carcinoma (metaHR = 2.14, 95%CI = 1.37–3.36), including ovarian cancer (metaHR = 2.61, 95% CI = 1.94–3.52)." (PMID 25748047, 2015). "The STOSE model is the first spontaneous HGSC model, as confirmed by the expression of immunohistochemical markers (pan-CK+, WT1+, inhibin−, PAX8+), consistent with human ovarian carcinomas." (PMID 24672774, 2014). "The negative expression of WT-1 and ER effectively excludes more common ovarian carcinoma types, such as high-grade serous carcinoma (typically WT-1+/ER+) and endometrioid carcinoma (typically ER+)." (PMID 41479789, 2025). "This open-label, non-randomized phase I study enrolled patients with WT1-expressing ovarian cancer in second or third remission from June 2016 to July 2017." (PMID 36900251, 2023). "In this study, the expression of CDH1 was significantly reduced after down-regulation of WT1, which indicates that in SKOV3 ovarian cancer cells, down-regulation of WT1 to promote its migration and invasion may be partly by inhibiting the expression of CDH1." (PMID 34692659, 2021). "In this study, the down-regulation of WT1 increased YAP1 mRNA expression, which may promote the migration and invasion of the SKOV3 ovarian cancer cell line." (PMID 34692659, 2021). "Restricting studies to antigen-based methods did not alter the results, which indicated that WT1 was not an independent prognostic marker for ovarian cancer." (PMID 25748047, 2015). "Overexpression of WT1 -KTS isoform, and not other WT1 isoforms, has also been proven to increase migration and invasion in human ovarian cancer cells." (PMID 23298185, 2013).
ovarian carcinoma (continued). "Wilms tumor 1 (WT1) is an oncogenic zinc-finger transcription factor with low expression in the BM and notable overexpression in various hematological malignancies (AML and CLL), as well as in several solid tumors (such as glioblastoma, mesothelioma, and ovarian cancer)." (PMID 40610404, 2025). "Based on the absence of WT1 expression, this cluster most likely contained cells from the clear cell component of the tumour, which is another histopathological type of epithelial ovarian cancer characterised by a worse prognosis compared to HGSTOCs." (PMID 34238352, 2021). "Determination of WT1 expression by an immunohistochemical method on ovarian carcinoma specimens showed that around 50% of ovarian carcinoma samples possessed a high level of WT1 expression and the expression level had a negative impact on the survival rate of this cancer." (PMID 33110919, 2020). "Results showed that WT1 positive expression could only predict poor outcomes for ovarian cancer in univariate model, but not in multivariate model." (PMID 25748047, 2015). "Due to the fact that WT1 gene has been shown to be transcriptionally regulated by some upstream transcriptional factors like Sp1, PAX2, PAX8 and PEA3, it is worthwhile to further analyze the expression status of these upstream molecules in ovarian cancer specimens obtained from this population." (PMID 16606472, 2006). "Our study findings showed that WT1 may not only participate in the regulation of the migration and invasion of ovarian cancer cells through the ERK1/2 pathway, but may also participate in the migration and invasion of ovarian cancer cells by regulating these three signal pathways." (PMID 34692659, 2021). "Furthermore, the possibility of primary ovarian cancer was considered based on the CK7 positive, CK20 negative, calretinin negative, WT-1 positive, CEA nonspecific and ER nonspecific findings." (PMID 24397776, 2014).
mesothelioma (89 papers, 2004 to 2025). A usually malignant and aggressive neoplasm of the mesothelium which is often associated with exposure to asbestos. "Because of the specific expression of nuclear WT1 in mesothelioma, immunohistochemical staining for WT1 is used as a diagnostic marker to distinguish mesothelioma from lung cancer." (PMID 39116074, 2024). "A review that analyzed 88 published papers listed WT1 as one of the most specific diagnostic markers for mesothelioma with 96% specificity." (PMID 38026668, 2023). "A combination of two “mesothelioma-associated” markers (e.g., calretinin, Wilms’ tumor-1 (WT-1), cytokeratin 5/6) and two “(adeno)carcinoma-associated” markers (e.g., CEA, Ber-EP4, MOC-31) can typically be used to diagnose epithelioid mesotheliomas." (PMID 38136277, 2023). "Mutations in the WT1 gene have also been associated with pulmonary dysplasia, hypoplastic lung malformation, diaphragmatic hernia, decreased mesothelial cell entry into the lung, and mesothelioma." (PMID 30965570, 2019). "The value of WT1 as a diagnostic marker for mesothelioma has been previously confirmed." (PMID 24987706, 2014). "Several clinical trials employing peptide- or dendritic cell-based cancer vaccines targeting WT-1 are currently ongoing for the treatment of mesothelioma alone or in combination with immunotherapy (ClinicalTrials.gov ID: NCT04040231, NCT02649829, NCT05765084)." (PMID 40236706, 2025). "Mesothelin is expressed in the majority of epithelioid mesothelioma cases, whereas WT1 is expressed in both epithelioid (70%–100%) and sarcomatoid (10%–45%) mesothelioma." (PMID 40918456, 2025). "Prior to this event, the pleura was involved in an epithelial malignancy, which was immunohistochemically negatively stained with anti-D2-40, WT-1, or anti-calretinin antibodies, which are positive markers of mesothelioma." (PMID 40034201, 2025). "Preliminary biopsy results for our patient were positive for WT1, calretinin, and D2-40, leading to the initial diagnosis and treatment of mesothelioma." (PMID 39968515, 2025). "Antibodies that can detect mesothelioma expression markers, including calretinin, WT1, D2-40, and CK5/6, were chosen." (PMID 38938650, 2024). "The engrafted tumor retained key mesothelioma features, including strong positivity for Pancytokeratin, Calretinin, and WT1, as well as typical expression patterns for mesothelioma Mesothelin and EMA." (PMID 39768223, 2024). "This study investigated the role of IHC staining of BAP1, WT1, and calretinin and panels of their combinations in mesothelioma tumor tissue samples in predicting prognosis and response to chemotherapy in PM patients." (PMID 38280040, 2024). "In our examples, tumor-selective mRNAs in the HNCs (EGFR, CDH1) were stable, however, mesothelioma-selective mRNAs (i.e., mesothelin and WT1) were reduced." (PMID 38744944, 2024). "Our study suggests that the enhancement of WT1-specific immunogenicity of mesothelioma cells by ONX-0914 was due to the inhibition of the internal disruptive cleavage of the WT1235 epitope peptide." (PMID 39116074, 2024). "This mouse model develops tumours positive for WT1, a marker for mesothelioma, 75 days post induction." (PMID 37938546, 2023). "Wilms tumor protein (WT1) has been investigated as a cancer vaccine candidate in the domain of mesothelioma therapy because of its potential to activate CD8 WT1 and CD4-targeted responses." (PMID 37469419, 2023). "HAND2 expression coincided with differential expression of the previously mesothelium- and mesothelioma-associated genes MSLN and WT1, as well as with GATA5 and MEIS2." (PMID 35354817, 2022). "In mesothelioma treatment field, Wilms’ tumor suppressor gene (WT1) has been studied as cancer vaccine due to its ability to induce CD4 and CD8 WT1-specific reactions." (PMID 35785199, 2022).
mesothelioma (continued). "As overexpression of the Wilms’ tumour 1 (WT1) transcription factor occurs in several malignancies, including mesothelioma, WT1 peptide analogue vaccines have been developed to elicit CD4+ and CD8+ T cell responses." (PMID 34226685, 2021). "Mesothelioma can present with adenoid structures, but it is closely related to the pleura and expresses mesothelial markers (e.g. calretinin, D2-40, and WT-1) in the tumor components." (PMID 34350112, 2021). "As expected, mesothelioma cancer markers KRT5 and WT1 were upregulated in mesothelioma compared to mesothelium." (PMID 32664372, 2020). "Among the positive mesothelioma markers, WT1 showed the highest specificity of 98.6%, but sensitivity was limited to 86.2%." (PMID 29317712, 2018). "Although the majority of both DSRCTs and mesotheliomas express WT1, only rarely and weakly do DSRCTs express calretinin." (PMID 27403364, 2016). "Because DSRCTs generally express WT1 and are commonly located on peritoneal surfaces like mesotheliomas, authors have attempted to define DSRCTs as “a blastematous tumor derived of primitive mesothelium”." (PMID 27403364, 2016). "Characterization of the four tumor models by immunohistochemical markers revealed that, although the staining was moderate and heterogeneous, all tumor cells exhibited positivity for WT1, a common positive mesothelioma marker." (PMID 27129173, 2016). "NCI-Meso18, which was derived from an epithelioid mesothelioma, retained moderate expression of calretinin and minimal expression of mesothelin and WT1." (PMID 25952750, 2015). "The expression of mesothelioma-related markers (D2-40, Calretinin, Keratin 5/6, WT1, and Methotheioma-Ab1) was investigated in 87 cases of meningiomas and compared to EMA expression." (PMID 24987706, 2014). "Although pankeratin and D2-40 can be positive in both malignancies, as also demonstrated in a number of our cases, calretinin, keratin 5/6, keratin 7, and WT1 are typically distinguishing mesotheliomas." (PMID 24986479, 2014). "The negative to rare expression of well-established mesothelioma-related markers (Calretinin, Keratin 5/6, and WT1) demonstrated in meningioma cases in our study contrasts with their known patterns of expression in mesothelioma." (PMID 24987706, 2014). "The diagnosis of malignant mesothelioma in humans can be supported by staining for proteins commonly expressed in mesotheliomas, including calretinin, cytokeratins, mesothelin, WT-1 and podoplanin (D2-40)." (PMID 24405760, 2014). "A full mesothelioma panel, including WT1 and/or D2-40, is recommended to better define a mesothelial lineage." (PMID 24860692, 2014). "In this study, the expression of well-established mesothelioma markers (Calretinin, Keratin 5/6, and WT1) in addition to new markers (D2-40 and Mesothelioma Ab1) was investigated in 87 meningioma cases and compared to EMA expression." (PMID 24987706, 2014). "Immunohistochemical markers, that is, pankeratin, keratin 5/6, calretinin, and Wilms Tumor-1 (WT-1), are useful to confirm mesothelioma while carcinoembryonic antigen, CD15 and thyroid transcription factor-1 (TTF-1) are negative markers." (PMID 24198994, 2013). "The tumor showed typical immunohistochemical phenotypes of mesothelioma, positive for WT-1, calretinin and CK5/6." (PMID 22505977, 2009). "Again, immunohistochemistry can help in the differentiation of mesothelioma and markers such as mesothelin, cytokeratin 5/6, calretinin, thrombomodulin and WT-1 have been used." (PMID 19099560, 2008). "The main TAAs in mesothelioma are mesothelin and the Wilms Tumor-1 (WT1) protein." (PMID 40918456, 2025). "Indeed, all mesothelioma cell lines of mesothelial origin examined in this study expressed high levels of WT1." (PMID 39116074, 2024).
mesothelioma (continued). "Tumours of approximately equal size arising in lenti-Cre induced mice with and without asbestos were compared by IHC for expression of cell lineage markers (pan-cytokeratin, vimentin and smooth muscle actin) along with Ki67 and the commonly used mesothelioma markers WT1 and Mesothelin." (PMID 37441092, 2023). "In addition, the mesothelial marker, Wilms’ tumour 1 (WT1), is commonly coexpressed with MSLN and immunoreactivity is similarly associated with improved survival in mesothelioma." (PMID 37040900, 2023). "Similarly, since mesothelioma cancer cells often have an abundant expression of WT1 (Wilms’ tumor suppressor gene), a trial using dendritic cells (DC) targeting WT1, in conjunction with chemotherapy (platinum/pemetrexed), is ongoing." (PMID 37445594, 2023). "IHC characteristics were consistent with MM clinico-pathological features, including diffuse positivity for calretinin and focal positivity for WT1 for mesothelioma, focal positivity for CK5/6, wide positivity for D2-40 for epithelial carcinoma, and negative for MOC31 adenocarcinoma." (PMID 35036082, 2022). "Finally, RNA sequencing of KPM cells comparative to normal pleural mesothelial cells revealed a distinctive transcriptomic signature that included classic mesothelioma markers (Msln, Spp1, Efemp1, Pdpn, Wt1) as well as new candidate mesothelioma genes." (PMID 34898002, 2022). "Similarly, expression of CR, and WT1 confirmed the nature of the second model tumor being mesothelioma." (PMID 34789172, 2021). "Various genes that are characteristically found in the developing and established mesothelial structures are also extremely valuable as markers in the diagnosis of mesotheliomas allowing to discriminate malignant mesotheliomas from, for instance, adenocarcinomas (e.g., cytokeratin and WT1)." (PMID 30965570, 2019). "Wilms tumour 1 (WT1) is expressed in most cases of mesothelioma." (PMID 28817839, 2017). "Calretinin and WT1 were negative while Keratin 5/6 and Mesothelioma-Ab1 were weakly expressed in classical variants (5.7% and 3.4%, resp)." (PMID 24987706, 2014). "The University Hospital of Antwerp has started a similar protocol in mesothelioma and several other solid tumours but is using WT-1 as antigen loading for the DCs (ClinicalTrials.gov Identifier: NCT01291420), circumventing the need for patient's tumour material." (PMID 22778767, 2012). "WT1 might also decorate nuclei of both epithelioid or biphasic mesothelioma but in general, WT1 stain most frequently epithelioid mesotheliomas." (PMID 15777480, 2005). "In human mesotheliomas, WT1 may promote cell proliferation, migration, and chemoresistance." (PMID 38026668, 2023). "Likewise, the expression of WT1 in a female patient can guide the diagnosis either to an ovarian serous carcinoma or malignant mesothelioma; whereas WT1 expression in a male will strongly favour a mesothelioma." (PMID 29621151, 2018). "Conversely, the PM harbored a relative low number of genetic variants and a novel mutation in the WT1 gene that might be involved in the carcinogenesis of nonasbestos-related mesothelioma." (PMID 27902597, 2016). "The proteins that were unique to mesothelioma samples (cell line and PE samples) were MAGED4, PRAME, WT1, ACRBP, EPHA2 and SOX11." (PMID 39921204, 2025). "On the other hand, mesothelioma classically stains positive for calretinin, CK5 or CK5/6, WT1, and D2-40." (PMID 39968515, 2025). "However, if the immunopeptidome presented by MHC-I can be altered by the use of selective immunoproteasome inhibitors such as ONX-0914, the type and amount of neoantigen-derived epitopes other than WT1 may be altered and the immunogenicity of mesothelioma cells may be enhanced." (PMID 39116074, 2024). "Tumor expressed three mesothelial markers, WT1, D2-40 and CK5/6, confirming the diagnosis of mesothelioma." (PMID 39434853, 2024).